QARS1 (glutaminyl-tRNA synthetase 1)
Description:
Glutamine--tRNA ligase. Plays a critical role in brain development.
Synonyms: GlnRS; QARS; MSCCA; PRO2195
Tractability: PROTAC: ubiquitination databases record sites on it; a small molecule that binds it is known.
Target class: Enzyme; Ligase
Gene: Protein-coding gene on chromosome 3 (49,095,932 to 49,105,130, reverse strand). Ensembl gene ENSG00000172053.
Subcellular location: Cytoplasm, cytosol; Cytoplasm
Subcellular location (Human Protein Atlas): Cytosol
Pathways (Reactome):
Metabolism of proteins: Cytosolic tRNA aminoacylation; Mitochondrial tRNA aminoacylation
Developmental Biology: Transcriptional and post-translational regulation of MITF-M expression and activity
Metabolism: Selenoamino acid metabolism
Gene Ontology:
Molecular function: glutamine-tRNA ligase activity; protein binding; protein kinase binding; protein kinase inhibitor activity; aminoacyl-tRNA ligase activity; ATP binding; nucleotide binding
Biological process: brain development; glutaminyl-tRNA aminoacylation; negative regulation of apoptotic signaling pathway; negative regulation of DNA-templated transcription; negative regulation of stress-activated MAPK cascade; tRNA aminoacylation for protein translation; translation; tRNA aminoacylation
Cellular component: aminoacyl-tRNA synthetase multienzyme complex; cytoplasm; cytosol; protein-containing complex; mitochondrial matrix
Genetic constraint (gnomAD): Loss-of-function variants: 79 observed, 111.57 expected, observed/expected ratio (o/e) 0.71, 90% interval 0.59 to 0.85. The upper end of that interval is the gene's LOEUF score, 0.85, which puts it in group 3 of 6, group 1 being the genes least tolerant of losing a copy. Missense variants: 966 observed, 1,044.9 expected, observed/expected ratio (o/e) 0.92, 90% interval 0.88 to 0.98. Synonymous variants: 395 observed, 388.54 expected, observed/expected ratio (o/e) 1.02, 90% interval 0.94 to 1.11.
Gene-disease validity (ClinGen):
ClinGen rates the evidence that QARS1 causes each of these diseases.
diffuse cerebral and cerebellar atrophy - intractable seizures - progressive microcephaly syndrome (autosomal recessive): Definitive.
Homologues: Orthologues: chimpanzee QARS1 (99% identical), macaque QARS1 (96% identical), pig QARS1 (94% identical), rabbit QARS1 (93% identical), dog QARS1 (93% identical), rat Qars1 (91% identical), guinea pig QARS1 (90% identical), mouse Qars1 (90% identical), tropical clawed frog qars1 (78% identical), zebrafish qars1 (74% identical), Drosophila melanogaster GlnRS (58% identical), Caenorhabditis elegans qars-1 (56% identical). Paralogues in human: EPRS1 (29% identical), EARS2 (12% identical).
Diseases named in the same sentence as QARS1 in open-access papers:
QARS1 is named in the same sentence as 11 diseases in open-access papers, as found by Europe PMC text mining. Sharing a sentence is not in itself a finding about the gene and the disease. The quoted sentences say what the papers report.
microcephaly (9 papers, 2016 to 2025). A congenital or acquired developmental disorder in which the circumference of the head is smaller than normal for the person's age and sex. "Studies have shown that mutations in QARS1 (encoding human glutaminyl-tRNA synthetase) are associated with epilepsy, developmental decline, progressive microcephaly, and brain atrophy." (PMID 40493339, 2025). "Here, we report a case of two siblings from India having DEE, progressive microcephaly, and intractable epilepsy due to homozygous QARS1 mutation." (PMID 40034633, 2025). "Reference to OMIM (Online Mendelian Inheritance in Man) suggested that microcephaly, progressive, seizures, and cerebral and cerebellar atrophy (OMIM#615760) are caused by homozygous or compound heterozygous mutations in the QARS1 gene (OMIM*603727)." (PMID 40034633, 2025). "Pathogenic variants in QARS1 (MIM:603727; Glutaminyl-TRNA Synthetase 1), which encodes Glutaminyl-tRNA synthetase 1, have been associated with rare progressive microcephaly with seizures and cerebral and cerebellar atrophy (MSCCA MIM:615760)." (PMID 40448856, 2025).
Cerebellar atrophy (2 papers, 2020 to 2025). Cerebellar atrophy is defined as a cerebellum with initially normal structures, in a posterior fossa with normal size, which displays enlarged fissures (interfolial spaces) in comparison to the foliae secondary to loss of tissue. "Microcephaly with cerebellar atrophy was reported to result from defects in glutaminyl-tRNA synthetase 1 (QARS1) or defects in seryl-tRNA synthetase 1 (SARS1)." (PMID 33102526, 2020).
breast carcinoma (1 paper, 2025). "Compared with that in normal breast cells, AIMP2 expression was high in breast cancer cells, whereas QARS1 expression was low in breast cancer cells; the expression of IYD was not clear." (PMID 40493339, 2025). "Furthermore, this study revealed evidence suggesting that QARS1 may influence breast cancer cell proliferation through methionine metabolism." (PMID 40493339, 2025). "Analysis of breast cancer gene expression data from the TCGA database revealed that the expression of AIMP2 and IYD was elevated in breast cancer tissues, whereas the expression of QARS1 was elevated in normal tissues." (PMID 40493339, 2025).
breast tumour (1 paper, 2025). "Consequently, inhibition of QARS1 may occur during breast tumorigenesis, which aligns with the findings of our study, and it could impact the proliferation of breast tumour cells by modulating methionine metabolism." (PMID 40493339, 2025).
epilepsy (1 paper, 2024). A brain disorder characterized by episodes of abnormally increased neuronal discharge resulting in transient episodes of sensory or motor neurological dysfunction, or psychic dysfunction. "Identifying potentially pathogenic variants like those found in SCN9A and QARS1, as well as frequently co‐occurring combinations like RYR3 and RANBP2, offers valuable insights into the genetic foundations of epilepsy." (PMID 39509559, 2024). "Identifying specific pathogenic variants in genes such as SCN1A, SCN9A, and QARS1 and the recurrent combination of RANBP2 and RYR3 variants underscores the necessity for ongoing research to elucidate their roles in epilepsy development." (PMID 39509559, 2024).
tumor (3 papers, 2020 to 2025). "The findings revealed notable enrichment of AIMP2 and IYD in tumour cells, whereas QARS1 was enriched in immune cells." (PMID 40493339, 2025). "Notably, certain scholars have reported that QARS1 gene expression is lower in tumours than in normal breast tissue." (PMID 40493339, 2025). "Remarkably, specific aaRS genes do show a DNA profile reminiscent of an oncogene (e.g., GARS1, AIMP2, and YARS2) or tumor suppressor (e.g., NARS1, QARS1, LARS2, and RARS2)." (PMID 33266490, 2020).
cancer (1 paper, 2020). A tumor composed of atypical neoplastic, often pleomorphic cells that invade other tissues. "For example, QARS1 is overexpressed in many cancer types, while its alterations at the DNA level are mostly deletions and mutations." (PMID 33266490, 2020).
neurological disorders (1 paper, 2025). "Mutations in QARS1 have been linked not only to neurological disorders but also to impaired lymphocyte proliferation." (PMID 40649814, 2025).
QARS1 also shares sentences with these, for which no sentence is quoted: Ataxia (1 paper); Brain atrophy (1); Developmental Epileptic Encephalopathy (1).